TBC1D20 (TBC1 domain family member 20)
Description:
GTPase-activating protein (GAP) specific for Rab1 and Rab2 small GTPase families for which it can accelerate the intrinsic GTP hydrolysis rate by more than five orders of magnitude. Also shows GAP activity for RAB18 GTPase. Promotes RAB18 dissociation from the endoplasmic reticulum (ER) membrane into the cytosol, probably through stimulating RAB18 GTP-hydrolysis. Involved in maintaining endoplasmic reticulum structure.
Synonyms: C20orf140; dJ852M4.2; WARBM4
Tractability: Small molecule: a structure with a bound ligand is known. Antibody: UniProt predicts a signal peptide or a membrane-spanning region. PROTAC: ubiquitination databases record sites on it.
Gene: Protein-coding gene on chromosome 20 (423,596 to 462,566, reverse strand). Ensembl gene ENSG00000125875.
Subcellular location: Membrane
Pathways (Reactome):
Vesicle-mediated transport: COPII-mediated vesicle transport; TBC/RABGAPs
Gene Ontology:
Molecular function: GTPase activator activity; protein binding; small GTPase binding
Biological process: COPII-coated vesicle cargo loading; endoplasmic reticulum to Golgi vesicle-mediated transport; Golgi organization; host-mediated activation of viral genome replication; positive regulation by virus of viral protein levels in host cell; positive regulation of ER to Golgi vesicle-mediated transport; positive regulation of GTPase activity; regulation of cilium assembly; virion assembly; vesicle organization; vesicle-mediated transport
Cellular component: endoplasmic reticulum; endoplasmic reticulum membrane; Golgi membrane; nuclear membrane; endoplasmic reticulum-Golgi intermediate compartment membrane; membrane
Genetic constraint (gnomAD): Loss-of-function variants: 12 observed, 41.51 expected, observed/expected ratio (o/e) 0.29, 90% interval 0.18 to 0.47. The upper end of that interval is the gene's LOEUF score, 0.47, which puts it in group 2 of 6, group 1 being the genes least tolerant of losing a copy. Missense variants: 421 observed, 521.17 expected, observed/expected ratio (o/e) 0.81, 90% interval 0.75 to 0.88. Synonymous variants: 205 observed, 205.59 expected, observed/expected ratio (o/e) 1, 90% interval 0.89 to 1.12.
Homologues: Orthologues: chimpanzee TBC1D20 (99% identical), macaque TBC1D20 (99% identical), pig TBC1D20 (98% identical), dog TBC1D20 (95% identical), rabbit TBC1D20 (94% identical), mouse Tbc1d20 (93% identical), guinea pig TBC1D20 (92% identical), rat Tbc1d20 (88% identical), tropical clawed frog tbc1d20 (76% identical), zebrafish tbc1d20 (74% identical), Drosophila melanogaster CG17883 (34% identical), Caenorhabditis elegans tbc-20 (30% identical).
Diseases named in the same sentence as TBC1D20 in open-access papers:
TBC1D20 is named in the same sentence as 14 diseases in open-access papers, as found by Europe PMC text mining. Sharing a sentence is not in itself a finding about the gene and the disease. The quoted sentences say what the papers report.
Warburg micro syndrome (10 papers, 2014 to 2024). Micro syndrome is an autosomal recessive disorder caracterised by ocular and neurodevelopmental defects and by microgenitalia. "Mutations in human TBC1D20 gene cause Warburg Micro syndrome, and one of the main symptoms is visual impairment." (PMID 36712873, 2022). "Loss of function of TBC1D20 is involved in Warburg Micro syndrome, a disease that is characterized amongst others by cataracts in the lens cause by lack of removal of damaged proteins and organelles from lens fiber cells." (PMID 31527750, 2019). "RAB18, RAB3GAP1, RAB3GAP2 and TBC1D20 are each mutated in Warburg Micro syndrome, a rare autosomal recessive multisystem disorder." (PMID 26063829, 2015). "Together with previous reports, this indicates that Warburg Micro syndrome can be caused directly by loss of RAB18, or indirectly through loss of RAB18 regulators RAB3GAP or TBC1D20." (PMID 26063829, 2015). "Mutations in RAB18, RAB3GAP1, RAB3GAP2, and TBC1D20 have caused Warburg micro syndrome, a rare autosomal recessive multisystem disorder, suggesting that RAB3GAP1, RAB3GAP2, and TBC1D20 might play roles in PRRSV-2 replication." (PMID 38607975, 2024). "Mutations in TBC1D20 (TBC1 domain family member 20), a gene associated with the autosomal recessive disorder Warburg Micro syndrome 4 characterized by congenital abnormalities in the eye (including cataracts), brain, and genital organs, show impaired autophagy." (PMID 37034386, 2023). "Warburg Micro Syndrome (WARBM, ORPHA: 2510), also known as Micro Syndrome, is a RD caused by mutations in RAB3GAP1 and TBC1D20 genes." (PMID 37160609, 2023).
cataract (6 papers, 2014 to 2023). Partial or complete opacity of the crystalline lens of one or both eyes that decreases visual acuity and eventually results in blindness. "Blind sterile (bs) mice carry a Tbc1d20-null mutation and exhibit cataracts and testicular phenotypes similar to those observed in WARBM4 patients." (PMID 25476608, 2014). "Recently, we reported that blind sterile (bs) mice, initially identified over 30 years ago as a spontaneous autosomal recessive mouse mutation exhibiting cataracts and male infertility, carry a loss of function mutation in the Tbc1d20 gene." (PMID 25476608, 2014). "Besides, loss-of-function mutations in TBC1D20 cause cataracts in blind sterile mice." (PMID 26187041, 2015). "TBC1D20 mutation (TBC1D20 protein as a GTPase-activating protein (GAP) for RAB1 and RAB2) causes cataracts and male infertility in patients with WARBM." (PMID 37160609, 2023). "A study conducted on mice tested what would happen if TBC1D20-mediated autophagic flux was altered and found that the animals presented cataracts in the lens nucleus, but the cortex remained transparent." (PMID 33673657, 2021). "In mice, the disruption of Tbc1d20 results in vacuolated cataracts and a defect in acrosomal formation resulting in male infertility." (PMID 25476608, 2014). "Our findings show that the disruption of Tbc1d20 in mice results in cataracts and aberrant acrosomal formation, thus establishing bs and Tbc1d20ZFN/ZFN as allelic variants." (PMID 25476608, 2014). "Therefore, alteration of the autophagic flux mediated by TBC1D20 resulted in the accumulation of autophagic material in the lens fibers and the formation of cataracts." (PMID 33673657, 2021). "Mice lacking Tbc1d20 or Tdrd7 develop cataracts with disrupted autophagic flux and delayed differentiation in lens fiber cells." (PMID 37034386, 2023).
male infertility (4 papers, 2014 to 2023). The inability of the male to effect fertilization of an ovum after a specified period of unprotected intercourse. "Mice with defective Tbc1d20 develop blindness and male infertility." (PMID 32976492, 2020). "Loss of function mutations in the gene responsible for TBC1D20 (TBC1 domain family, member 20) have been shown to cause autosomal recessive Warburg micro syndrome 4, which involves eye, brain, and endocrine abnormalities in humans, and male infertility with nuclear cataracts in blind-sterile mice." (PMID 36766820, 2023).
developmental delays (1 paper, 2019). "Interestingly, we found that most of the affected patients with developmental delays were caused by the defects of multiple genes which were usually associated with TBC1D20, SOX12, and NRSN2 genes." (PMID 31087544, 2019). "Among the affected cases on ClinVar database, 16 patients with 20p13 microdeletion exhibited TBC1D20 gene deletion (16/52, 30%), and 10 out of them (63%) were reported to have developmental delays, suggesting the importance of TBC1D20 gene for neurological development." (PMID 31087544, 2019).
Hepatitis (1 paper, 2023). Inflammation of the liver. "For example, it is known that the Rab1-activating protein TBC1D20 is involved in the hepatitis C, HIV-1 and HSV replication cycle and especially Rab1B plays an important role in Ebola virus particle assembly and ER-to-Golgi transport of the vesicular stomatitis virus glycoprotein." (PMID 37112806, 2023).
TBC1D20 also shares sentences with these, for which no sentence is quoted: atherosclerosis (1 paper); Blindness (1); cancer (1); cardiac failure (1); Crohn disease (1); Martsolf syndrome (1); nuclear cataract (1); Sepsis (1); skin cutaneous melanoma (1).